CD63 (CD63 molecule)
Diseases named in the same sentence as CD63 in open-access papers (continued):
Sharing a sentence is not in itself a finding about the gene and the disease.
cancer (continued). "Exosomes contain a variety of transmembrane proteins (e.g., CD63, CD9, CD81) and cancer-associated biomarkers (e.g., EpCAM, EGFR)." (PMID 39943486, 2025). "It has been revealed that CD63 interacts with latent membrane protein 1 (LMP1) of Epstein-Barr virus to facilitate the package of LMP1 into exosomes derived from infected cancer cells." (PMID 40640922, 2025). "Recent studies have shown that tumors communicate with platelets through small extracellular vesicles (sEVs), which deliver cancer biomarkers in a CD63-dependent manner and activate platelets, ultimately leading to thrombosis." (PMID 40052128, 2025). "Although both CD63 and PROM2 are implicated in mitigating ferroptosis through EV-mediated ferritin expulsion in various cancer models, indeed, their regulation is different." (PMID 40177133, 2025). "Yet, overexpression of TIMP1 by various cancer types has been associated with increased disease severity and pro-metastatic effects, partly mediated by TIMP1/CD63/ITGB1 activation of focal adhesion kinase (FAK) signaling." (PMID 40265926, 2025). "Alternatively, a novel strategy using human-specific anti-CD9 or anti-CD63 antibodies has been adopted to deplete circulating cancer-derived EVs." (PMID 38495881, 2024). "By crossing the Flp-driven KPF with the ExoBow allele, termed KPF-CD63-mCherry, we achieved Flp-mediated expression of CD63-mCherry specifically in cancer cells (Pdx1-Flp; R26CD63-XFP/+; FSF-KrasG12D/+; Trp53Frt/+)." (PMID 38383468, 2024). "The expression of CD63 dramatically decreased in cancer cells (HepG2, MDA-MB-231 and PC3) after receiving 1 h of cannabidiol treatment, suggesting that the underlying mechanism involves its interference with CD63." (PMID 38243280, 2024). "We show that cancer associated fibroblasts (CAFs), endothelial and immune cells received PDAC CD63+ Exos in the tumors of KPF CD63-mCherry and KPC-ExoBow mice." (PMID 38383468, 2024). "Lastly, these results suggest that EVs from cancer cells and stem cells display cell type-specific expression of CD63, CD9, and CD81." (PMID 38786083, 2024). "Extracellular immunofluorescence staining revealed increased surface exposure of CD63 at the cancer cell side of the IS, suggestive of the fusion of MVBs with the plasma membrane." (PMID 39380986, 2024). "Conventional methods use antibodies such as CD44 and CD63 to isolate cancer cells or cancer-related substances, such as exosomes, from biological fluids (e.g., blood) for subsequent analysis." (PMID 38400238, 2024). "First, IHF results showed that PD-L2 exhibited higher colocalization with CD63 in cancer tissues than in paired adjacent tissues, indicating that PD-L2 is secreted by cancer cells." (PMID 39511147, 2024). "For further examination, after the isolation of exosomes from cancer cells, we detected the exosomal marker CD63 by western blotting." (PMID 38627767, 2024). "It was found that CD63 was mainly expressed in the cell membrane of cancer cells and in the cytoplasm of stromal cells." (PMID 39703839, 2024). "To further understand the phenotypic changes occurring upon cancer exosomes uptake in the two major cell type targeted by PDAC CD63+ Exos, we exposed an ex-vivo-established CAFs cell line and an endothelial cell line (bEnd.3) to cancer exosomes." (PMID 38383468, 2024). "Other series have also described that CD63 levels are inversely related to cancer invasion and metastases." (PMID 39430073, 2024). "The LOD of FI‐based assays for detecting cancer cell‐derived EVs in F‐PBS using FITC‐labelled CD63‐BP aptamer was determined as 2.0 × 108 HT‐29 EVs/mL, the LOD using FITC‐labelled HER2‐HApt aptamer was 5.0 × 108 SKBR3 EVs/mL." (PMID 39221546, 2024). "The proposed electrochemical biosensor used two surface proteins (CD63 and EpCAM) as detection markers to distinguish four different types of cancer cells (4T1, Hela, HepG2, and A549)." (PMID 37050576, 2023).
cancer (continued). "TSPAN1, TSPAN3, TSPAN12, TSPAN31, CD82 and CD63 have also been reported to reduce chemosensitivity of cancer cells." (PMID 36941633, 2023). "Exosomes derived from PRP are a promising source for this purpose, as they contain various membrane proteins, including CD63, and lack cancer-stimulating activities." (PMID 38188010, 2023). "The communication between CAFs and cancerous cells is facilitated by exosomes, including CD-63, which can lead to scirrhous cancer." (PMID 37834127, 2023). "TIMP-1 can also act as a signaling molecule on the cell surface receptor CD63, activating downstream signaling pathways and paving the way for cancer pathogenesis." (PMID 37629569, 2023). "CD63 is a member of the tetraspanin membrane protein family and used as a marker for predicting and monitoring the prognosis of cancers and other diseases." (PMID 36746944, 2023). "Exosomes carry specific proteins (CD9, CD81, CD63, ALIX, TSG101, and HSP70), nucleic acids (DNA, miRNA, lncRNA, and circRNA), lipids, and metabolites with cancer information, making them potential cancer diagnostic biomarkers." (PMID 37016296, 2023). "(F’’) Merge; note the striking colocalization between the MVB marker CD63 and β-catenin in advanced stages of cancer (inset)." (PMID 37902809, 2023). "Pie charts represent the expression profiles of CD9, CD81 and CD63 in percentage of circulating EV particles from representative cancer patients and LC control." (PMID 36582804, 2022). "The mode of action of CBD involves its interference with CD63 expression, as a lower CD63 expression level was observed after CBD treatment in three cancer cell lines." (PMID 36446847, 2022). "Further, to validate the IHC result, flow cytometric analysis for exosomes detection with CD63 antibody depicted increased levels of CD63 in the cancer cells in comparison to the normal cells." (PMID 35496046, 2022). "We have demonstrated that basophils can be identified within whole blood samples taken from cancer patients and can be activated ex vivo to upregulate cell surface CD63 with IgE-mediated (anti-FcεRI, anti-IgE) and with innate (fMLP) stimuli." (PMID 35159247, 2022). "We can assess ex vivo if the cancer patients’ basophils can be triggered and upregulate expression of the CD63 cell surface marker when incubated with a therapeutic drug." (PMID 35159247, 2022). "The number of 6 μm size fraction of cancer-derived EVs correlated negatively with the CD63 and CD81 expression in NTHY cells, as well as positively with angiogenesis in vitro." (PMID 35328683, 2022). "We used anti‐human CD63 magnetic beads to capture cancer‐derived EVs of human origin in mouse circulating EVs, since the anti‐human CD63 magnetic beads did not recognize mouse CD63." (PMID 35923105, 2022). "In particular, several evidences reported the ability of TIMP-1 to protect cancer cells from apoptosis and induce epithelial-to-mesenchymal transition by binding its receptor CD63." (PMID 36140255, 2022). "It has been shown that exercise can attenuate the expression of exosome CD63, which stimulates T-cells and is presented as a prognostic marker for cancer." (PMID 36362598, 2022). "EVs, such as exosomes, and EV‐related molecules such as CD63 offer new targets for early cancer diagnostics due to the EVs being aberrantly modified by cancer cells." (PMID 34423573, 2022). "It was shown that the level of CD63 expression was extremely high in cancer cell lines such as PC3, PC-3M-luc, MDA-MB-231-luc-D3H1, and MDA-MB-231-luc-D3H2LN, which have a high metastatic ability." (PMID 36354675, 2022). "As TIMP-1 is only able to trigger intracellular signaling pathways and modulate cell behavior through its interaction with CD63 and β1-integrin, the formation of TIMP-1/CD63/β1-Integrin complex became an interesting target for cancer research." (PMID 34502227, 2021).
cancer (continued). "Coupling the magnetic nanobead capturing technology with SRS, a developed SRS was investigated for recognizing and detecting CD63 as a general cancer biomarker." (PMID 34940275, 2021). "Efforts have been made to fabricate a self-referenceable platform specifically for detecting and quantifying cancer-derived exosomal biomarker CD63." (PMID 34940275, 2021). "Small EV/particle fractions (10–70 nm) were protein-rich with CD63, HSP90α, and HSP90β and highly transferred palmGFP to receiver cancer cells and reduced the viability." (PMID 34071980, 2021). "Increased CD63-positive exosomes in patients with cancer are reported; therefore, CD63 is suggested as a cancer biomarker for diagnosis and prognosis." (PMID 34359304, 2021). "In the next stage, a single step in situ detection of CD63 and miR-21 in cancer EVs produced from HeLa cells was tested using flow cytometry." (PMID 33477255, 2021). "For single step biomarker detection in the cancer cell-derived EV cluster, EVs from HeLa cells were incubated with CD63 antibody and MB-21, in the absence or presence of DSPE-PEG-DSPE." (PMID 33477255, 2021). "They used their biosensor to screen two exosome biomarkers (CD9 and CD63) and four cancer biomarkers (CD24, CD44, EpCAM, and human epidermal growth factor receptor 2 (HER2))." (PMID 34940275, 2021). "In a new sandwich-type biosensor developed for cancer diagnosis, functionalized magnetic beads with anti-CD63, anti-EpCAM, and horseradish peroxidase catalysis were applied." (PMID 34940275, 2021). "CD63 antibody and molecular beacon-21 were investigated for multiplexed biomarker detection in normal and cancer EVs." (PMID 33477255, 2021). "Specifically, cancer cell line conditioned media containing exosomes and free proteins were first incubated with three different fluorescent aptamers against CD63, EpCAM and MUC1 on AuNPs (~ 9.2 nm)." (PMID 34855021, 2021). "Other efforts produced a CD63-fuctionalized reduced graphene oxide field effect transistor biosensor to quantify cancer-derived exosomes in low-concentration samples (33 particles/μL) electrically." (PMID 34940275, 2021). "For example, tetraspanin CD63, an integrin-binding partner exclusively present on exosomes, expression correlates inversely with the cancer metastasis." (PMID 34572899, 2021). "For the case of fibroblast cells associated dataset, the most significant pathway obtained was Proteoglycans in cancer (p value 1.2 × 10−3) (CD63, DDX5, DCN, LUM, ITGB1)." (PMID 34071236, 2021). "As a proof of concept, Alexa Fluor® 488-conjugated anti-CD63 antibody and molecular beacon-21 targeting miR-21 were investigated for multiplexed biomarker detection in healthy vs cancer-derived EVs using flow cytometry." (PMID 34855021, 2021). "13–21, CD63/HSP90-positive) involve an efficient molecular transfer from macrophage-EVs to receiver carcinoma cells." (PMID 34071980, 2021). "Inhibition of αvβ3 integrin decreases CD63 expression in cancer cells suggesting an effect on SEV content." (PMID 32988382, 2020). "CD63 aptamers have been also conjugated with QDs for the labelling of EVs for super-resolution microscopy and as part of a cancer-derived EV detection system using clinical serum samples." (PMID 32002172, 2020). "In this study, an enzyme-linked immunosorbent assay (ELISA) demonstrated that both cancer-derived Reg-EVs and Br-EVs bind to LDL, based on lipoprotein-mediated masking of a well-known EV surface protein, CD63." (PMID 33160390, 2020). "We next attempted to visualize the biodistribution of circulating cancer-derived exosomes by subcutaneously transplanting PC3/CD63-Antares2 cells into nude mice." (PMID 33024173, 2020). "Cancer cells generate copious levels of exosomes; the Munc13-4 is a Ca2+-dependent regulator of Rab-dependent signaling, which confers increased CD63+, CD9+, and ALIX+ exosomal release in cancer cells, which enhances their survival." (PMID 32957534, 2020).
cancer (continued). "Glutamine depletion induces a switch in the balance of exosome marker secretion in cancer cells from CD63 to Rab11a, a result observed with two very different EV isolation methods." (PMID 32720716, 2020). "WB analysis showed enrichment of exosome-related proteins, CD9 and CD63, in the EVs isolated from both cancer and control samples when compared with EV-depleted supernatant." (PMID 31963351, 2020). "The CD63-Antares2 xenograft mouse model will be useful for elucidating the dynamics of cancer-derived exosomes in vivo and evaluating the therapeutic efficacy and mechanism of exosome production inhibitors." (PMID 33024173, 2020). "Taken together, these results suggested that the xenograft mouse model bearing CD63-Antares2-expressing cancer cells is suitable for in vivo evaluation of drugs designed to inhibit exosome secretion." (PMID 33024173, 2020). "This method provides promising results for the detection of exosomes containing specific exosomal markers, such as CD63 or cancer-specific proteins." (PMID 30987213, 2019). "We measured the CD63 to identify exosomes and used mortalin antibody via Western blot analysis to measure mortalin protein expression level from several types of cancer patient plasma." (PMID 33833900, 2019). "It was shown that the release of CD63+ exosomes by cancer cells largely dictated this response, where exosomes can always be found ahead of invading cancer cells and are actively incorporated into the infiltrated mesothelium." (PMID 30345394, 2018). "Here, mapping the transcriptome of cancers treated with CDDP by scRNA‐seq, we uncovered a novel gene, COX7B, associated with platinum‐resistance, and surrogate marker, CD63." (PMID 30367559, 2018). "This study aimed to clarify the relationship between CD63 expression in cancer cells and stromal cells and clinical-pathologic factors." (PMID 30222750, 2018). "The CD63 expression in stromal cells was significantly correlated with CD63 expression in cancer cells (p<0.0001)." (PMID 30222750, 2018). "Cancer cells influence distant normal cells via exosomes, and CD63 plays a role in metastatic niche formation." (PMID 30222750, 2018). "Findings from the NTA analysis, showing significant reduction in EMV release, particularly exosome release, was further assessed by Western blotting of CD63 expression in all three cancer cell lines following CBD treatment (5 μM)." (PMID 30150937, 2018). "According to the analysis for each stage, the OS rates of stage III and stage IV patients with CD63 expression in cancer cells were significantly worse than those with CD63-negative expression (p < 0.0001 and p = 0.0063, respectively)." (PMID 30222750, 2018). "Of 595 patients, 247 cases had CD63-positive cancer cells, and 107 cases had CD63-positive stromal cells." (PMID 30222750, 2018). "CD63 expression was mainly observed on the cell membranes of cancer cells, and in the cytoplasm of stromal cells." (PMID 30222750, 2018). "In sum, the results from both cell line experiments demonstrated that COX7B and CD63 were closely related in cancers." (PMID 30367559, 2018). "Based on their results, oral-cancer-derived exosomes presented a variable size (20–400 nm), a higher intervesicular aggregation, and possess a higher expression of CD63 molecules compared to normal saliva exosomes." (PMID 29890622, 2018). "This interesting approach of exploiting CD63 for cancer immunotherapy is based on its role in intracellular trafficking and abundance in exosomes." (PMID 29946318, 2018). "We then examined the effects of the chemical chaperones on EVs from cancer cells by bioluminescence imaging and quantified the expression of CD63 in these EVs." (PMID 28929569, 2018). "Although the CD63-positive rate in stromal cells was less than that on cancer cells, patients with advanced cancer expressed CD63 in stromal cells as well as on cancer cells." (PMID 30222750, 2018).
cancer (continued). "It has been shown that prostate basal epithelial cells do not express the characteristic CD antigens of secretory cells, however the expression levels of CD63 found in cancer cells are similar to that of secretory cells." (PMID 27903962, 2017). "In humans, anti-CD9 and CD63 antibodies cannot selectively attach to cancer-derived EVs, so further investigations are needed." (PMID 29238879, 2017). "Some investigations support that CD63 is a cancer metastasis suppressor, while the functional role of CD63 needs more evaluation." (PMID 28977990, 2017). "Using fluorophore-conjugated antibodies, we set out to measure expression levels of the exosomal surface marker CD63 and other cancer-related proteins shown in our mass spectrometry analyses of exosomes, such as CD44 and CD47." (PMID 27819324, 2016). "It is important to note that similar SPR signals were observed during CD9 and/or CD63 capture for both cancer and healthy patient samples." (PMID 27464736, 2016). "Studies that are based on endogenously produced EVs have used either genetically engineered cancer cell lines, which produced GFP-tagged CD63, or human cancer xenografts in mice, where cancer-derived EVs were located by detecting human CD63." (PMID 28936238, 2015). "NT’s main contribution was obtaining proof of the relationship between CD63 and anti-cancer drug resistance." (PMID 24884960, 2014). "Taken together, our results support the possibility that glycosylated CD63 by RPN2 plays an important role in cancer malignancy through the regulation of protein localization." (PMID 24884960, 2014). "The relationship between CD63 and cancer cell malignancy has previously been reported; however, the exact contribution of CD63 to cancer malignancy is poorly understood." (PMID 24884960, 2014). "The tetraspanin CD63 is a highly N-glycosylated protein that is known to regulate cancer malignancy." (PMID 24884960, 2014). "The cell surface expression of other tetraspanin members that play prominent roles in cancer cell invasion including CD63, CD81, and CD151 were unaffected by CD9 overexpression." (PMID 23840773, 2013). "CD63 is also involved in cancer progression and has been suggested as a predictive biomarker for some cancers." (PMID 24351670, 2013). "Our finding that Luminal-A and ER-positive tumors have higher CD63 expression could indicate that vesicles could also transmit information from this group of cancer cells." (PMID 39430073, 2024). "Moreover, CD9 was enriched in “immune system;” CD63 was enriched in “transport and catabolism” and “cancers: overview;” CD81 was enriched in “infectious diseases: parasitic,” “infectious diseases: viral” and “immune system” by KEGG pathway analysis." (PMID 38725025, 2024). "Western blotting revealed CD9, CD81, and CD63 in normal and cancer Exos." (PMID 39206404, 2024). "In addition, the average count and heterogeneity of CD63 per CFSE+CD63+ sEV derived from the two cancer cell types (PC3 and A549) is notably higher than those in CFSE+CD63+ sEV derived from the two noncancerous cell types (RBC and HEK293)." (PMID 39665317, 2024). "The abnormally high expression of RPN2 in a variety of cancer subtypes plays an important role in the drug resistance and invasion progression of cancer cells by regulating the N-terminal glycosylation of various proteins such as p-glycoprotein, CD63, and epidermal growth factor receptor (EGFR)." (PMID 35265520, 2022). "CRISPR/Cas9 knockout of CD63 in Epstein-Barr virus infected cancer cells resulted in reduced secretion of EVs that were positive for the viral protein LMP1, and severely impaired packaging of those vesicles, concomitant with a disruption in the perinuclear localization of LMP1." (PMID 35223551, 2022).